IL21 (interleukin 21)
Diseases named in the same sentence as IL21 in open-access papers (continued):
Sharing a sentence is not in itself a finding about the gene and the disease.
tumor (continued). "Other types of CAR-T cells, such as 4/15NKG2D-CAR and IL-4/IL-21 ICR, also show anti-tumor activity; the former converts IL-4 inhibitory signals downstream into IL-15 activation signals, while the latter activates the STAT3 pathway." (PMID 39958351, 2025). "Through interleukin-6 (IL-6), TGF-β, and interleukin-21 (IL-21), the TME stomach myofibroblasts stimulate Th17 differentiation, which by secretion of IL-17 will promote tumor progression." (PMID 39940924, 2025). "Accumulated tumor antigen-specific LIGHT+CXCL13+IL-21+ Tfh cells and TLS decreased tumor growth in a CD4+ T cell and CXCL13-dependent manner." (PMID 40475770, 2025). "Tumor cells induce inflammation by activating white blood cells and releasing inflammatory cytokines (e.g., TNF-α, IL-1β, IL-6, IL-21, and TGF-β), which are critical at the tumor site." (PMID 41153842, 2025). "Fourth-generation CARs that incorporate cytokines (IL-7, IL-15, or IL-21) increase CAR-T-cell persistence, tumor targeting, and antitumor activity." (PMID 41019073, 2025). "However, the PD-L1/PD-1 pathway may inhibit the anti-tumor effects of IL-21." (PMID 39958351, 2025). "For instance, co-expressing IL-15 or IL-21 in CAR-T cells has been explored to enhance persistence and mitigate exhaustion, thereby improving their anti-tumour efficacy." (PMID 40624498, 2025). "In the flow cytometry assay, the expression of IL-21, IL-27, and IFNA2 proteins with anti-tumor functions were elevated significantly in DBMSCs after treatment with MDA231 cells compared to the untreated DBMSCs." (PMID 39768220, 2024). "In summary, the therapeutic effects of both MWA and IL-21 rely on CD8+ T cells, and their combination further augments the anti-tumor potential of CD8+ T cells." (PMID 38833177, 2024). "IL-21 regulates the function of CD8+ T cells through the tumor necrosis factor-α (TNF-α)/IL-17 pathway, mediating tumor regression." (PMID 39534095, 2024). "tested the effects of IL-21 in combination with monoclonal antibodies (mAbs) for CTLA-4 and PD-1 regulatory receptors after tumor establishment in several mouse models." (PMID 38638431, 2024). "IL-2/IL-21 provided a survival effect via downregulation of the pro-apoptotic protein, BIM, which they posit contributes to improved anti-tumor function through a survival benefit to iNKT cells." (PMID 39170618, 2024). "Craft and Joshi’s team found that B cells presenting tumor antigens can promote the differentiation of tumor-specific helper CD4+ T cells, producing IL-21, enhancing anti-tumor CD8+ T cell responses, and thereby controlling tumor growth." (PMID 38696324, 2024). "Here, tumor control depended on CD8+ T cells, Erb-IL-21 selectively expanded existing intratumoral PD-1intTim-3- CD8+ functional T cells." (PMID 38638431, 2024). "Through their secretion of IL-21, TFH cells promote malignant B-cell proliferation and survival, and their proportions among PBMCs are correlated with tumor load." (PMID 39273028, 2024). "Our simultaneous administration of IL-21 and anti-PD-1 mAbs after MWA can effectively inhibit tumor growth in mice." (PMID 38833177, 2024). "In our study, to enhance the anti-tumor activity of CAR-NK cells, we modified the CAR-NK cells expressing IL-21, which has been reported to increase the anti-tumor immunity in NK cells." (PMID 38263004, 2024). "On the other hand, Th17 cells inhibit tumor angiogenesis by secreting TNF-α, IFN-γ, IL-17F, IL-21 and IL-22, which inhibit tumor growth and promote the apoptosis of cancer cells." (PMID 39534095, 2024). "Th17 cells can suppress tumor growth and metastasis and promote cancer cell apoptosis by secreting TNF-α, the soluble dimer cytokine interferon (IFN)-γ, IL-17, IL-21, and IL-22." (PMID 39534095, 2024). "Here, we reported that VVL expressing GM-CSF and IL-21 and VVL-GL21 had outstanding effectiveness in combating aggressive PaCa tumor growth even in high tumor burden." (PMID 39830516, 2024).
tumor (continued). "Local administration of MSCs secreting IL-21 into B-cell lymphoma BALB/c murine models was reported to prolong anticancer effects, inhibiting the formation of tumour nodules." (PMID 39416732, 2024). "IL-21 increases the proliferation and function of NK and CD8+ T cells, thereby enhancing their cytotoxic effects against tumor cells." (PMID 39456897, 2024). "In another study, CD4 T cell-derived IL-21 induced the expansion of strongly cytolytic CX3CR1+ CD8 TILs, which promoted tumor control." (PMID 37189417, 2023). "IL-21’s capacity to stimulate and expand cytotoxic CD8+ T cells, NK cells, and NKT cells also confers powerful anti-tumor characteristics." (PMID 37759505, 2023). "In TLN, Caprin-1 suppressed activation of lymphocytes, T cell activation and anti-tumor cytokine and chemokine (IFNG, IL1B, IL21 and TNF) production." (PMID 38082307, 2023). "While the production of IL-21 and CXCL13 by Tfh cells can stimulate adaptive anti-tumour immunity at a distance, the direct engagement of Tfh cells with B cells through ICOS/ICOSL and CD40L/CD40 binding is also critical to the anti-tumour immune response." (PMID 37936700, 2023). "According to their discoveries, the intratumoral microenvironment expression of IL-21 increased the level of CD8+ T–cell-related responses and led to the suppression of tumor growth." (PMID 36742134, 2023). "When the levels of IL-21 in the blood diminished, the inhibitory effect of CRA on tumor growth in tumor-bearing mice declined." (PMID 37081540, 2023). "IL-21 released by IL-1β-stimulated TH9 cells induced IFNγ secretion from CD8 and NK cells in tumor-bearing mice, resulting in tumor growth inhibition." (PMID 37189417, 2023). "Further mechanistic studies showed that in the mouse LUAD model, TfH cells produce IL-21, which is essential for tumor control and CD8+ T cell effector function in tumor invasion." (PMID 37315289, 2023). "We studied the γc cytokines IL-2, IL-7, IL-15 and IL-21 or IFN-γ, as these cytokines have been shown to stimulate anti-tumor immunity." (PMID 37923822, 2023). "Interleukin (IL)-21 is a cytokine produced by activated conventional CD4+ T lymphocytes and natural killer T cells, driving anti-tumor immunity in the skin and kidney." (PMID 38001643, 2023). "Collectively, IL-21 as a monotherapy and in combination or fusion with other vaccines, cytokines or antibodies can increase the function of NK and CD8+ T-cells in the tumor, suggesting drug development based on IL-21 has a bright future." (PMID 36936961, 2023). "IL-21 expression in mice induced NK- and T cell-dependent secretion of IFN-γ and tumor-restrictive activity." (PMID 35884974, 2022). "B cells promote the differentiation of tumor-specific CD4 Tfh cells depending on neoantigens, strengthen CD8 T-cell effector abilities by producing IL-21 and finally promote antitumor immunity." (PMID 35719407, 2022). "The presence of IL21 stimulated CD8+ infiltrated cells and boosted tumor-antigen specific cytotoxic activity." (PMID 35323193, 2022). "Il-21 is a cytokine in the TME that can promote T cell proliferation and drive the T cell memory effect and has the function of preventing tumor metastasis or recurrence." (PMID 35935930, 2022). "T lymphocytes mediate tumor immunity by secreting various cytokines into the TME, such as IL-2, IL-4, IL-5, IL17, IL-21, IL-22, and IFN-γ." (PMID 35464411, 2022). "In a murine model of lung adenocarcinoma, B cells were found to promote tumor-specific CD4+Tfh cell differentiation, which then produced IL-21 to enhance CD8+T cell responses to drive anti-tumor immunity." (PMID 36465392, 2022). "designed ChPD1-T cells for recognizing and damaging tumor cells by secreting inflammatory factors such as IL2, IL-17, IL-21, IFN γ, TNF, and GM-CSF and decreasing the inflammatory suppressor cytokine IL-10." (PMID 35935930, 2022). "IL-21 also plays a pivotal role in triggering CD8+T cell function and tumor regression in the lung adenocarcinoma model." (PMID 36246629, 2022).
tumor (continued). "IL-17, IL-21, IL-22, TNF-α and IL-6 are also produced in excess in individuals with CRC and synergistically promote tumor growth." (PMID 35739324, 2022). "In a comparative evaluation of IL2, IL15 and IL21, recombinant IL21 was shown to enhance and sustain CD8+ T-cell activity against tumor cells." (PMID 35323193, 2022). "IL-21 fused to anti-PD-1 antibody stimulated generation of Tscm with enhanced cell proliferation and tumor-specific CD8+ T cells, outperforming anti-PD-1 antibody and IL-21 infused as separate treatments." (PMID 35432319, 2022). "Wang reported on the novel IL-4 and IL-21 incorporation of inverted cytokine receptor (ICR), which enhances the efficacy of CAR-T cells in the IL-4 tumor environment." (PMID 36291802, 2022). "In this study, our data show that BATF, one of the downstream targets of IL-21 signaling, is necessary for CD8+ T cell effector differentiation and anti-tumor function." (PMID 33809259, 2021). "We next compared the differences in the IFN-γ+CD4+ and IL-21+CD4+ T cell frequencies between tumor and adjacent non-tumor tissues." (PMID 34026621, 2021). "Our previous findings have demonstrated that IL-21-producing CD4+ T cell ACT augments the effector CX3CR1+ CD8+ TIL population, resulting in enhanced tumor control." (PMID 33809259, 2021). "While most studies suggest that diverse NKT cells inhibit anti-tumour immunity, iNKT cells contribute to natural tumour surveillance with immediate cytokine secretion (IFN-γ, TNF, IL-13, IL-17, IL-4, IL21, IL-22) and FasL/TRAIL pathways." (PMID 33499101, 2021). "Indeed, it costimulates T and natural killer (NK) cell proliferation and function and regulates B cell survival and differentiation and the function of dendritic cells, suggesting that IL-21 may represent a potentially useful agent for the development of tumor immunotherapies." (PMID 34684029, 2021). "Taken together, Tfh cells played anti-tumor role via CXCL13-dependent recruitment of CD8+ T cells and B cells and IL-21-dependent B cell maturation." (PMID 34359579, 2021). "Because IL-21R expression is induced and sustained in Cbx3/HP1γ-deficient CD8+ effector T cells without exogenous IL-21, we posit that whether IL-21 production is high or low during tumor development, it can still positively affect Cbx3/HP1γ-deficient CD8+ T-cell effector functions." (PMID 34721405, 2021). "Tfh cells promoted the formation of an immunoactive tumor microenvironment by secreting CXCL13 and IL-21, and the high infiltration of Tfh cells correlated with better patient prognosis." (PMID 34359579, 2021). "IL-21, produced predominantly by activated CD4+ T cells, has been reported to promote T cell-mediated tumor rejection and has pleiotropic effects on immunity via the IL-21 receptor." (PMID 34853180, 2021). "Compared with that in healthy donors, the ability of cTfh cells to express effector factors CXCL13 and IL-21 in patients with PDAC was significantly impaired and was further impaired in higher tumor stages." (PMID 34359579, 2021). "In this study, we found that Basic Leucine Zipper ATF-Like Transcription Factor (BATF), a transcription factor downstream of IL-21 signaling, is critical to maintain CD8+ T cell effector function within the tumor." (PMID 33809259, 2021). "A vaccine construct consisting of OVA antigen and +/− IL-21 induced greater CTL proliferation and effector cytokine IFN-γ expression with IL-21 in OVA expressing tumours in mice via a PI3K and mTORC1 pathway." (PMID 34960140, 2021). "Accordingly, tumor explants from 10 patients with HNSCC were divided evenly into 2 groups according to the cutoff points for PD-L1 and IL-21 described in the methods section." (PMID 34026621, 2021). "Our results revealed the important role of Tfh cells in mediating anti-tumor cellular immunity and humoral immunity in PDAC via secreting CXCL13 and IL-21 and determined a novel mechanism of immunosuppression in PDAC." (PMID 34359579, 2021).
tumor (continued). "In an aggressive B16F10 murine melanoma model, IL-21 secretion stimulated by CD4+ TH cells drives CD8+ T cell differentiation towards CX3CR1+ cytotoxic effector phenotype and anti-tumor activity." (PMID 34012451, 2021). "More recently, our findings suggest that IL-21-producing CD4+ T cells are required for the formation of effector CX3CR1+ CD8+ TILs, which enhances tumor control." (PMID 33809259, 2021). "Chimeric switch receptor were also designed by combining the IL-4R extracellular domain with the intracellular signaling domains of IL-7 or IL-21, resulting in CAR T cells with enhanced anti-tumor activity against IL-4+ tumors." (PMID 33746981, 2021). "Th9 cell-derived IL-9 and IL-21 further enhance the ability of CTL and NKT cells to secrete IFN-γ, thereby promoting tumor cell killing." (PMID 34944921, 2021). "attempted to introduce new therapies based on Th17 lymphocytes which produce IL-17A, IL-17F, IL-21, IL-22, IL-26, IL-6, TNF-α and suppress tumour progression through enhanced antitumor immunity in OC." (PMID 34621670, 2021). "IL-21 in iNKT cell ex vivo expansion cultures altered the iNKT cells enhancing cytotoxicity and persistence of CD62L+ CAR-iNKT with better tumour protection." (PMID 33499101, 2021). "For example, IL-21 derived from Th9 cells induces the production of IFN-γ by CD8+ and NK cells, which was required for the anti-tumor effects of Th9 cells." (PMID 33777008, 2021). "IL-21 promotes growth and angiogenesis of EBV-positive DLBCL tumours in a NOD/SCID mouse xenograft model." (PMID 32704112, 2020). "Tumor cytokines’ dynamics indicate that as the tumor grows, HMGB1, IFN-γ and μ1 (IL-6, IL-17, IL-21, IL-22) increase in density, but TGF-β and μ2 (IL-10, CCL20) stay relatively constant." (PMID 33291412, 2020). "The result claimed that IL7 and IL21 were superior to IL2 and IL15 in enhancing tumor eradication, although IL2 and IL15 established increased effector functions." (PMID 33381115, 2020). "IL-21 enhances tumor rejection in mice via NKG2D-dependent NK cell activity, suggesting IL-21 to be a possible target for immune escape induced by NKG2D elicitation." (PMID 32762681, 2020). "These cells produce various tumor-promoting cytokines, including TNF-α, IL10, and IL17A, and also the less well-studied cytokines such as IL21 and IL26." (PMID 31948053, 2020). "Phosphorylation of key tumor signaling pathways ERK and STAT3 was seen, in line with data on IL-21 signaling pathways in other cells, e.g., lymphocytes." (PMID 31540511, 2019). "Of note, inhibiting autophagy resulted in a significant decrease in the frequency of IL-10+ B cells, IL-21+ and IL-10+CD4+ T cells, as well as a significant increase in IFN-γ+CD4+ T cells, in the tumor-draining lymph nodes and tumor tissue." (PMID 31300052, 2019). "Among the predicted upstream regulators, we found IL-21, IFNA, and IFNG, factors reported to have antitumor effects in a variety of murine experimental tumor models." (PMID 31710308, 2019). "In this study, we have revealed that TRAPs can educate CD4+ T cells to promote tumor growth and metastasis through an HSP90α–TLR2–IL-6–IL-10/IL-21 axis and the induction of IL-10+ Bregs." (PMID 31300052, 2019). "Taken together, these results suggest that IL-6, IL-10, and IL-21 from TTRAP augment the differentiation and immunosuppressive function of TRAPs-induced B cells to facilitate tumor growth and metastasis." (PMID 31300052, 2019). "Upon administration, we suspect that these IL-21/IL-2-expanded TILs or TRUCKs would be best maintained by engineering them to secrete IL-7 and IL-15, which we hypothesize will further promote their persistence and memory recall responses to prevent tumor relapse in patients." (PMID 30842774, 2019). "Consistent with previous results, the frequencies of IL-10+ and IL-21+ CD4+ T cells and IL-10+ B cells in tumor-draining lymph nodes and tumor tissues from Il6−/− tumor-bearing mice were significantly decreased." (PMID 31300052, 2019).
tumor (continued). "In the mice bearing knock-down B16F10 tumors, the frequency of IL-21+ and IL-10+ CD4+ T cells in the tumor draining lymph node and tumor tissue and the serum IL-6 level were significantly reduced as compared to those in the mice bearing control tumors." (PMID 31300052, 2019). "Many cytokines, like IL-2, IL-15 and IL-21 were chosen to fuse with NKG2D because of their ability to promote immune cell functions and induce anti-tumor responses." (PMID 29316666, 2018). "NK cells expanded with stimulation with IL-2 and IL-21 in combination with EBV-LCL feeder cells, exhibited cytotoxicity against a variety of tumor targets." (PMID 30517188, 2018). "IL-21 drives IFN-γ secretion from both NK and CD8 T cells, which are both responsible for tumor elimination." (PMID 27832300, 2017). "Altogether, these studies suggest that TH9 cells trigger IL-9 and IL-21-dependent, CD8-dependent anti-tumor responses that favor tumor elimination." (PMID 27832300, 2017). "IL-21 drove IFN-γ secretion from both NK and CD8 T cells, which were both responsible for tumor elimination." (PMID 27832300, 2017). "When we intratumourally injected recombinant IL-21 (rIL-21) into MC38 H-2Kb and H-2Db KO tumour-bearing Rag1−/− mice, tumour growth was significantly inhibited with an increase in tumour-infiltrating NK cells." (PMID 28585539, 2017). "Prophylactic vaccination with IL-21 and IL-7 co-expressing B16F10 cells and tumor challenge were repeated in wild-type, CD4 knockout and CD8 knockout (KO) mice in this study." (PMID 27571893, 2016). "Experiments in the B16 model has shown that mixing IL-21 with IL-15 improves expansion of transferred tumor-antigen-specific CD8+ T cells and enhances tumor control after vaccination." (PMID 27656185, 2016). "Among the various cytokines, the combination of CART cells and IL-15 or IL-21 administration mediated the best anti-tumor response, followed by IL-2 and IL-7, whereas IL-18 and only CART cells treated mice had the heaviest tumor burden." (PMID 27409425, 2016). "IL-21 stimulates IFNγ production, enhances the cytolytic activity of NK cells, and increases CD8+CTL activity, all of which promote anti-tumor immunity." (PMID 27589682, 2016). "In line with the results of Th1 differentiation, combined treatment of anti-IL-4 and anti-IL-21 Abs significantly reversed the impaired induction and function of tumour-specific CD8+ T cells in response to tumour inoculation in aged mice." (PMID 25850032, 2015). "IL-21 was overexpressed in the colonic lesions of Apcmin/+ mice treated with AOM and killed on day 56 as compared to the non-tumor areas." (PMID 25839161, 2015). "Both Apcmin/+ (control) and IL-21-knockout (IL-21 KO)-Apcmin/+ mice were injected with AOM and monitored for tumor formation." (PMID 25839161, 2015). "In both control and IL-21 KO-Apcmin/+ mice, COX-2 RNA and protein were increased in the tumors as compared to non-tumor areas, though induction of COX-2 was markedly diminished in the absence of IL-21." (PMID 25839161, 2015). "Both IL-15 and IL-21 have been shown in multiple experiments to enhance the in vivo anti-tumor effects of CD8+ T cells and in some cases to potentiate tumor regression." (PMID 25903148, 2015). "The therapeutic use of IL-18 and IL-21 must, however, be carefully and extensively examined and developed as translational research, because it is well known that the cytokines transduce signals related to cellular survival, proliferation, and differentiation and, therefore, may help tumor growth." (PMID 25686210, 2015). "To assess the cellular source of IL-21 in human sporadic CRC, we isolated tumor infiltrating leukocytes (TILs) from patients who underwent surgical resection." (PMID 25839161, 2015). "Because of the promising results seen with IL-21 to date, we endeavored to discover whether B/I and IL-21 exposure alone or in combination with IL-7/15 would increase the expansion of naïve or antigen-sensitized T cells, and whether it would increase anti-tumor activity." (PMID 25903148, 2015).